CRP (C-reactive protein)
Diseases named in the same sentence as CRP in open-access papers (continued):
Sharing a sentence is not in itself a finding about the gene and the disease.
lymphopenia (continued). "Similarly, the risk associated with lymphopenia was not changed with additional adjustment for CRP level (age-, sex-, and CRP level quintile–adjusted HRs, 1.3 for ALC 1100/μL to 1500/μL [95% CI, 1.2-1.5] and 1.8 for ALC ≤1000/μL [95% CI, 1.6-2.1])." (PMID 31790569, 2019). "Laboratory markers show higher CRP elevation in SARS‐CoV‐2 cases, whereas lymphopenia is more characteristic of influenza A infection." (PMID 41583020, 2026). "Patients with SPM were older and less frequently had arthralgia, and exhibited a hyper-inflammatory phenotype [elevated CRP, serum ferritin (SF), LDH, neutrophil-to-lymphocyte ratio (NLR), KL-6], severe lymphopenia, and higher infection rates." (PMID 42292368, 2026). "During attacks, both PFAPA and SURF showed elevated CRP/ESR with neutrophilia/monocytosis and lymphopenia." (PMID 41972166, 2026). "Thrombocytopenia, neutropenia, lymphopenia, lymphocytosis, renal azotemia, and increased levels of SDMA and CRP were excluded from further analysis (p > 0.2)." (PMID 41471237, 2025). "Laboratory tests revealed moderate leukopenia (3700/mm3) with lymphopenia (800/mm3) and aneosinophilia, hepatic cytolysis (ALT = 155 U/L) and inflammatory syndrome (CRP = 10.5 mg/dL)." (PMID 40126322, 2025). "Parameters such as lymphopenia, elevated neutrophil-to-lymphocyte ratio (NLR), increased levels of C-reactive protein (CRP), and thrombocytopenia have been identified as markers of disease progression and poor outcomes." (PMID 40283596, 2025). "Laboratory testing, when reported, showed ferritin, C-reactive protein (CRP) and/or CK over the limits, together with leukopenia and/or lymphopenia." (PMID 40963624, 2025). "Baseline inflammatory markers, including CRP, RF, and VSG, were elevated in 40% of patients, while 40% also had grade 1 lymphopenia at baseline." (PMID 40461909, 2025). "The clinical and laboratory parameters consistently associated with adverse outcomes include advanced age, comorbidities, elevated levels of inflammatory biomarkers such as interleukin (IL-6) and C-reactive protein (CRP), and profound lymphopenia." (PMID 41235245, 2025). "Laboratory investigations demonstrated lymphopenia (0.4×109/L), hyponatremia (131 mmol/L), elevated erythrocyte sedimentation rate (ESR) (130 mm/h), normal CRP (6 mg/L), and stable renal function (creatinine 117 μmol/L)." (PMID 41431554, 2025). "During her initial presentation, her blood tests showed raised C-reactive protein (CRP) at 171 (0–4 mg/L), lymphopenia, and abnormal liver function tests." (PMID 40724633, 2025). "It highlights significant abnormalities such as lymphopenia, hyponatremia, and markedly elevated ESR, while CRP remained within normal limits." (PMID 41431554, 2025). "Elevated CRP levels have been correlated with decreased LMR, reflecting an immune imbalance characterized by relative lymphopenia and monocytosis." (PMID 41171774, 2025). "In addition, due to substantial missingness of CRP data and the absence of IL-6 measurements in our dataset, we were unable to validate the proposed inflammation-related mechanisms underlying hypoalbuminemia and lymphopenia." (PMID 40551734, 2025). "A number of hematological abnormalities were found in SCPs compared with NSCPs in the present study, including lymphopenia and low hemoglobin levels, hyperferritinemia, elevated serum LDH levels and raised circulating CRP levels." (PMID 38178206, 2024). "The patient had normal white blood cell counts, with lymphopenia, thrombocytopenia, hyponatremia, acidosis, and elevated brain natriuretic peptide (BNP), CRP, and erythrocyte sedimentation rate, with normal liver and kidney function." (PMID 39240972, 2024). "Our results show the predictive value of lymphopenia, thrombocytopenia, high NLR and CRP levels to evaluate the prognosis of COVID-19 pneumonia." (PMID 39659435, 2024).
lymphopenia (continued). "Laboratory parameters associated with an increased risk of developing severe clinical pictures include neutrophilia, lymphopenia, and increased levels of ALT, AST, LDH, CRP, and ferritin, which are consistent with our results." (PMID 39599799, 2024). "Among others, there are some basic parameters in laboratory findings, e.g., marked inflammation reflected by the elevation in C-reactive protein (CRP) and erythrocyte sedimentation rate (ESR) or lymphopenia." (PMID 38396888, 2024). "Other laboratory markers obtained in the acute phase of MIS-C have been associated with PICU admission, like elevated ESR (>30 mm/h), CRP (>5 mg/dL), ferritin, PCT, thrombocytopenia, lymphopenia, hyponatremia, and decreased serum albumin levels." (PMID 39338265, 2024). "Laboratory tests show elevated C-reactive protein (CRP) and normal white blood count (WBC) with lymphopenia." (PMID 39328662, 2024). "Laboratory findings showed leucopenia with neutropenia and lymphopenia, elevated lactate dehydrogenase (LDH) and ferritin levels, and mildly elevated erythrocyte sedimentation rate (ESR) and C-reactive protein (CRP)." (PMID 39744275, 2024). "These patients primarily experienced dyspnea and cough, and the most typical laboratory test results were elevated levels of C-reactive protein (CRP), PCT, D-dimer, ferritin, and lymphopenia." (PMID 36992139, 2023). "Previous research has identified lymphopenia, thrombocytopenia, increased D-dimer, LDH, and CRP as indicators and predictors of severe COVID-19 infection." (PMID 36103084, 2023). "At the same time, an elevated CRP (CPR > 5 mg/dl) and lymphopenia (lymphopenia described as lymphocyte < 800 cell/mm2) were confirmed as predictors of a possible evolution of the disease in a severe form." (PMID 38993895, 2023). "Laboratory features such as leukocytosis, lymphopenia, neutrophilia, NLR, PLR, CRP, LDH, D-dimer, ferritin level, and liver enzymes are significantly associated with the severity of the disease." (PMID 37900669, 2023). "Comparing the laboratory tests, patients who died had more pronounced lymphopenia and higher values of lactate dehydrogenase (DHL), ferritin, CRP, and d-dimer compared to those who survived." (PMID 38064470, 2023). "APLA-positive and APLA-negative patients who had lymphocytopenia presented higher levels of LDH activity, D-dimer, ferritin, and CRP at admission and 48 h later, and IL-6 was higher on admission than the reference values." (PMID 37626797, 2023). "In the univariate analysis, risk factors associated with disease severity were age, NLR, LMR, PLR, LCR, ferritin, LDH, CRP, D-dimer, RBC count, Hb, WBC count, neutrophilia, lymphopenia, PCV, urea, creatinine, and aminotransferases." (PMID 37900669, 2023). "This is consistent with the elevated pro-inflammatory cytokines/chemokines (TNF, IL-6, IL-1b, IL-8) serum levels elevated level of C-reactive protein (CRP), D-dimer and ferritin, and lymphopenia observed in patients with severe diseases." (PMID 38077399, 2023). "Children with MIS-C had high inflammation (median C-reactive protein [CRP] 16.0 mg/dL, IQR 7.8–24.0); lymphopenia (median absolute lymphocyte count of 0.91 × 103/mL, IQR 0.53–1.35); and coagulopathy (median D-dimer 3.1 mcg/mL, IQR 1.5–6.2)." (PMID 36282598, 2023). "The patients commonly present with complaints of fever, cough, and dyspnea, while the lab reports for the majority reveal decreased albumin, elevated C-reactive protein (CRP), lactate dehydrogenase (LDH), erythrocyte sedimentation rate (ESR), and lymphopenia." (PMID 36060437, 2022). "The medians of D-dimer level, lactate dehydrogenase (LDH), ferritin and C-reactive protein (CRP) were higher among ICU patients compared to their hospitalized counterparts, and ICU patients displayed a more evident neutrophilia and lymphopenia." (PMID 36451829, 2022). "Previous studies have extensively examined the lymphopenia, RDW, NLR, PLR, CRP, eosinopenia, and elevated lactate dehydrogenase (LDH) as predictors of mortality." (PMID 36062039, 2022).
lymphopenia (continued). "Analysis revealed a positive correlation for age, neutrophilia, lymphopenia, erythrocyte sedimentation rate (ESR), and C-reactive protein (CRP) with the emergence of neuroimaging abnormalities (p ≤ 0.018)." (PMID 35402993, 2022). "The persistent lymphopenia endotype had the highest age [median 61 years; interquartile range (IQR) 49–70], APACHE-II scores (median 19; IQR 15–24) and CRP level (median 58; IQR 14–132)." (PMID 35991659, 2022). "The most frequent findings in the laboratory results of patients and increase in C-reactive protein (CRP) (33.1%) and ferritin (18.2%), and lymphopenia (16%) were reported." (PMID 35875562, 2022). "Recent systematic reviews reported that most of PMIS patients had increased levels of one or more inflammatory markers, including CRP, PCT, ESR, ferritin, IL6, and D-dimer, accompanied by neutrophilia and lymphopenia." (PMID 36583110, 2022). "Lymphopenia, low SpO2 and albumin levels, elevated serum LDH, ferritin, urea, and CRP levels were found to be significantly correlated with severity CT score (P<0.0001)." (PMID 35802733, 2022). "Based on a meta-analysis, most abnormal laboratory tests in the first week of COVID-19 infection showed an increase of CRP, LDH, and lymphopenia consistent with our findings." (PMID 35096087, 2022). "Elevated TLC was observed in 14%, lymphopenia in 44%, elevated D-dimer in 81%, raised LDH in 29%, PCT in 25% and CRP in 67% of those pregnant patients." (PMID 35371473, 2022). "We found that poor prognostic factors such as advanced age, male gender, neutropenia, lymphopenia, low albumin, thrombocytopenia, and GFR and high AST, creatinine, LDH, CK, ferritin, CRP, procalcitonin, and D-dimer were common in these two groups." (PMID 35685537, 2022). "According to our study results, patients with high-risk FIB-4 scores were predominantly male, of advanced age, with neutropenia, lymphopenia, low albumin, thrombocytopenia, and GFR, and high AST, creatinine, LDH, CK, ferritin, CRP, procalcitonin, and D-dimer." (PMID 35685537, 2022). "Lymphopenia was more common in GBS-C+ (P = .025), and persisted even when the neurologic onset had followed the resolution of the antecedent infection, while CRP was at the limits of significance (P = .061)." (PMID 35905215, 2022). "In the slowly rising endotype, the APACHE score (median 18; IQR 13–22) and CRP level (median 52; IQR 14–130) were similar to those in the persistent lymphopenia endotype, while patients in the slowly rising endotype were younger (median 54 years; IQR 43–66)." (PMID 35991659, 2022). "Similar to the general population, the most common laboratory findings in pregnant women were high C-reactive protein (CRP) and procalcitonin levels (49-54%), lymphopenia (35%), and hyper-transaminasemia (16%)." (PMID 35359954, 2022). "Patients who have features of MIS-C without shock or cardiovascular dysfunction (fever, rash, lymphadenopathy, increased CRP/ESR, thrombocytopenia, lymphopenia) should be evaluated with both a laboratory panel and a cardiac evaluation (ECG, echocardiogram)." (PMID 35980407, 2022). "Elevations of inflammation-related proteins, such as C-reactive protein (CRP), ferritin and D-dimer, together with neutrophilia and lymphopenia have been shown to correlate with disease severity." (PMID 35453779, 2022). "At the time of TOC administration all patients had a hyperinflammatory state characterized by increased levels of IL-6, CRP, ferritin, LDH and/or D-dimers, as well as lymphopenia." (PMID 35268338, 2022). "Our case presented with the majority of the typical clinical manifestations of MIS-C, such as persistent fever, GI symptoms, lymphopenia, thrombocytopenia, elevated pro-BNP, and CRP." (PMID 35735756, 2022). "Common laboratory findings that were reported included lymphopenia, elevated lactate dehydrogenase (LDH) levels and elevated inflammatory markers such as C-reactive protein (CRP)." (PMID 33482780, 2021).
lymphopenia (continued). "Common laboratory findings include lymphopenia (83%), elevated inflammatory markers like erythrocyte sedimentation rate (ESR), C-reactive protein (CRP), ferritin, IL-1, and IL-6." (PMID 33925791, 2021). "All children in the present study had positive initial laboratory criteria for strongly suspected MIS-C, such as elevated CRP and/or ESR plus lymphopenia or thrombocytopenia or hyponatremia." (PMID 34208057, 2021). "Blood tests showed lymphopenia, hyponatremia, elevated creatinine, normal erythrocyte sedimentation rate (ESR), high CRP and high blood glucose level at time of admission." (PMID 33803475, 2021). "Previous studies have identified that lymphopenia, neutrophilia, elevated serum alanine aminotransferase (ALT), aspartate aminotransferase levels (AST), lactate dehydrogenase (LDH), D-dimer and C-reactive protein (CRP) all may be associated with disease progression and death." (PMID 33789703, 2021). "Lymphocytopenia(86%), elevated LDH (75%), elevated D-dimer (83%), elevated CRP (100%), andelevated procalcitonin (100%) were the most prevalent laboratory findings ininfected HD patients." (PMID 33836039, 2021). "The most prevalent laboratory findings are decreased albumin, high C-reactive protein (CRP), lymphopenia, increased platelets, increased lactate dehydrogenase, and a high erythrocyte sedimentation rate (ESR)." (PMID 34081600, 2021). "As for the analytical findings, bivariate analyses identified thrombocytopenia, lymphopenia and elevated serum LDH, CRP, ultrasensitive Troponin I, urea, and creatinine as significantly more common in deceased patients." (PMID 33467207, 2021). "Few studies have highlighted the prognostic value of blood findings such as lymphopenia, neutrophil/lymphocyte ratio, platelet/lymphocyte ratio, LDH, CRP, cardiac troponin, low-density lipoproteins and chest radiographic abnormality." (PMID 33482780, 2021). "Other prognostic factors have included dialysis vintage, thrombocytopenia, lymphopenia, and increased LDH or CRP level." (PMID 33466527, 2021). "Such broad changes in circulating inflammatory factors are also corroborated with elevation of the inflammatory markers, ferritin, and C-reactive protein (CRP), as well as significant lymphopenia due to the reduction of circulating CD4+ and CD8+ T-cells." (PMID 34201797, 2021). "• Most common: Increased levels of CRP (59.4%) and lactate dehydrogenase (LDH) (51.7%), low levels of albumin (58.6%) and lymphopenia (47.7%)." (PMID 34760713, 2021). "Upon admission, the presence of lymphopenia, mild hypertransaminasemia, and elevated lactate dehydrogenase (LDH) and C-reactive protein (CRP) stood out." (PMID 34494886, 2021). "We chose age and the top 5 variables extracted from PCA/PLS‐DA analysis including CRP, D‐dimer, LDH, prealbumin, lymphopenia for multivariable logistic regression model." (PMID 33112011, 2021). "Particularly, they have described hypoalbuminemia, increased C-reactive protein (CRP) and lactate dehydrogenase (LDH), lymphopenia, etc." (PMID 34031483, 2021). "Laboratory tests showed lymphopenia (0.9 109 cells/L IQR 0.6–1.2), increased D-dimer and C-reactive protein." (PMID 34770046, 2021). "Lymphopenia, including CD3, CD4, and CD8 T cell counts, resolved, with neutrophilia alleviation, and C-reactive protein (CRP), aspartate transaminase (AST), alanine transaminase (ALT), d-dimer, and bilirubin levels decreased." (PMID 34419143, 2021). "Within the first 4 days of hospitalization, the patient's condition gradually worsened, as shown by increased lymphopenia, WBC, neutrophil, CRP, and ferritin levels." (PMID 34950678, 2021). "The combination of lymphopenia, and increased LDH, INR, D‐dimer, CRP, and procalcitonin had a 96.9% (94.1%–98.4%) sensitivity." (PMID 33617117, 2021). "Some prognostic factors upon admission are lymphopenia and high levels of D-dimer (DD), lactate dehydrogenase (LDH), and C-reactive protein (CRP)." (PMID 33467585, 2021).
lymphopenia (continued). "The most significant hallmarks noted are raised C reactive protein (CRP) and lymphopenia, which are consistent with the inflammatory response produced by a virus." (PMID 32439731, 2021). "Serological investigations have indicated incidence of lymphopenia, neutrophilia, elevated CRP (C-reactive protein), ALT, AST, and D-dimer upon SARS-CoV-2 infection during pregnancy." (PMID 34816202, 2021). "The patient’s body temperature was 37.9 °C, C-reactive protein (CRP) level was 125 mg/dL (normal: 0–5 mg/dL), white blood cells (WBC) were 12,640/μL (normal: 5500–11,000/μL), and lymphopenia was present (0.81 x 103/μL)." (PMID 34177306, 2021). "Elevated inflammatory markers (ie, ferritin, CRP, D-dimer, fibrinogen, LDH, interleukin 6 [IL-6]), transaminitis, and lymphopenia were observed in all patients." (PMID 34548669, 2021). "In that study, the patients underwent the TPE procedure on the basis of CRS recognition (higher levels of ferritin, CRP, D-dimers, LDH and lymphopenia)." (PMID 34452349, 2021). "Lymphopenia, neutrophilia, and high levels of AST, BUN, CK, LDH, CTnI, ProBNP, Fbg, d-dimer, IL-6, CRP, procalcitonin, and serum ferritin were all significantly correlated with disease aggravation." (PMID 33850192, 2021). "Serum C reactive protein (CRP), erythrocyte sedimentation rate (ESR), fibrinogen, D-dimer, ferritin, lactatedehydegenase (LDH), interleukin 6 (IL-6) are increased; lymphopenia, thrombocytopenia, hypoalbuminemia and hyponatremia can be detected." (PMID 34773697, 2021). "Our laboratory findings showed that most patients presented lymphopenia, increased neutrophil count, and elevated levels of glucose, NT-proBNP, procalcitonin, cTnI, ALT, AST, LDH, CRP, and D-dimer." (PMID 33542929, 2021). "What is particular to this stage is the increase in inflammatory markers (CRP, LDH, IL-6, D-dimers, ferritin, prothrombin, troponin, NT pro BNP), as well as marked lymphopenia." (PMID 34201473, 2021). "In line with their findings, we found that patients with lymphopenia had lower TSH, fT4 and fT3, and higher CRP levels." (PMID 35095756, 2021). "These include a raised lactate dehydrogenase (LDH), inflammatory markers (e.g. ferritin [FER], C-reactive protein [CRP], aminotransferases and d-dimers) and lymphopenia." (PMID 33591793, 2021). "In a previous study, lymphopenia (31.4%), increased D-dimer (38.1%), depressed albumin (36.2%), elevated LDH (41.0%), and a high level of CRP (79.0%) were common among elderly patients with Covid-19." (PMID 34809556, 2021). "Multiple biochemical parameters are deranged when a patient is infected with coronavirus, with changes in C reactive protein (CRP) levels, lymphopenia, raised aminotransferases, creatinine kinase, and lactate dehydrogenase (LDH) among others." (PMID 34462686, 2021). "Most patients had altered laboratory findings, such as lymphopenia, elevated ferritin, LDH, C-reactive protein and d-dimer." (PMID 34113503, 2021). "The patient’s body temperature was 38.8 °C, CRP level was 224 mg/dL (normal: 0–5 mg/dL), WBC was 19,000/μL (normal: 5500–11,000/μL), and lymphopenia was present (0.43 x 103/μL)." (PMID 34177306, 2021). "Patients with severe infections have shown to have high inflammatory markers such as IL-6, CRP, D dimer, LDH and lymphopenia." (PMID 32664810, 2020). "Elevated CRP, ALT, neutrophil, urea, decrease albumin, lymphopenia, and IL-6 were also observed in worsening cases resulting in mortality, indicating progression into critically level with resulting liver and renal function test derangement." (PMID 33456651, 2020). "During the disease course, some patients developed leukopenia, lymphopenia, and thrombocytopenia with an upregulation of aspartate transaminase (AST), alanine aminotransferase (ALT), lactic dehydrogenase (LDH), and C-reactive protein (CRP)." (PMID 32098422, 2020). "Initial laboratory investigations revealed absolute lymphopenia and elevated D-dimer, lactate dehydrogenase (LDH), ferritin, and C-reactive protein (CRP)." (PMID 32918409, 2020).